RNU6-418P (RNA, U6 small nuclear 418, pseudogene)
Gene: Small nuclear RNA gene on chromosome 1 (205,595,041 to 205,595,147, forward strand). Ensembl gene ENSG00000206762.
Homologues: Orthologues: chimpanzee U6 (99% identical), macaque U6 (93% identical), pig U6 (71% identical). Paralogues in human: RNU6-727P (84% identical), RNU6-1094P (83% identical), RNU6-43P (83% identical), RNU6-884P (83% identical), RNU6-1243P (82% identical), RNU6-379P (82% identical), RNU6-1123P (81% identical), RNU6-1329P (81% identical), RNU6-1331P (81% identical), RNU6-454P (81% identical), RNU6-652P (81% identical), RNU6-97P (81% identical), and 1285 more.